TNF (tumor necrosis factor)
Diseases named in the same sentence as TNF in open-access papers (continued):
Sharing a sentence is not in itself a finding about the gene and the disease.
Insulin resistance (continued). "TNF-α and IL-6, as proinflammatory factors, from obese adipose tissue contribute to insulin resistance by impairing insulin receptor activation, upregulating insulin and insulin-like growth factor-1 (IGF-1) levels." (PMID 35964108, 2022). "TNF-α is the first pro-inflammatory cytokine involved in insulin resistance, but limited data can show that TNF-α is involved in glucose regulation in humans." (PMID 35757707, 2022). "TNF-α has been proposed as the link between neuroinflammation and the development of insulin resistance and type 2 diabetes mellitus." (PMID 36290695, 2022). "We noticed that the BSME decreased the expression levels of insulin resistance and macrophage chemoattractant proteins, such as TNF-α, IL-6, leptin and STAT-6, in maturing-adipocyte-secreted proteins." (PMID 35209178, 2022). "Both TNF-α and IL-6 can lead to insulin resistance by triggering different key steps in the insulin signalling pathway." (PMID 36501129, 2022). "TNF inhibitors appear to mainly act as insulin-sensitizing agents by attenuating TNF-α-induced insulin resistance, particularly in patients with a high degree of insulin resistance." (PMID 35629988, 2022). "One study revealed that mitochondrial ROS generated by activated macrophages stimulated the expression of IL-1β, TNF-α, and CCL-2, thereby increasing the risk of developing high-fat-induced insulin resistance and atherosclerosis." (PMID 36558562, 2022). "Adiponectin has insulin sensitivity, which is related to insulin resistance and can reduce the secretion of tumor necrosis factor-α (TNF--α), fat accumulation, and inflammatory mediators in the liver." (PMID 35992537, 2022). "Subsequent hypoxic leads to the recruitment of macrophages in adipose tissue and dysregulated expression of adipokines (such as TNF-α), further aggravating insulin resistance in adipose tissue." (PMID 36496995, 2022). "Some studies have shown that TNF-α is associated with an increased risk of developing T2D, acting through an intersection of the TNF-α and insulin signaling pathways to induce insulin resistance." (PMID 35055191, 2022). "miR-222 also promotes inflammation and insulin resistance through the tumor necrosis factor (TNF)-alpha-mediated pathways." (PMID 36432575, 2022). "sTWEAK has been shown to protect from insulin resistance by down regulating the TNFα induced increase in the activity of Protein phosphatase 2 (PP2A)." (PMID 34542797, 2022). "It has been reported that these adipokines are the key mediators of insulin resistance because they suppress insulin activity (especially TNF-α)." (PMID 35320949, 2022). "The amelioration of insulin resistance was claimed under the mechanism of regulating intestinal flora to reduce tumor necrosis factor-α (TNF-α), interleukin-6 (IL-6), and hypersensitive C-reactive protein (HS-CRP) in plasma." (PMID 35529925, 2022). "The mechanism of L-acetylcarnitine is also related to AMPK, inhibiting TNF-α-induced insulin resistance in skeletal muscle cells via the AMPK pathway." (PMID 35795562, 2022). "In a study of Mcp1 knock-out mice, a high-fat diet was unable to induce hepatic steatosis and insulin resistance, and adipose tissue produced less TNF-α." (PMID 36145221, 2022). "Many cell-extrinsic factors that promote insulin resistance, including hyperinsulinemia, TNFα, and high nutrients lead to excessive production of ROS19,76–78." (PMID 36473871, 2022). "Cancer expansion triggers the release of proinflammatory cytokines such as IL-1, IL-6, and TNF-α, which in turn increase lipolysis, muscle breakdown, and insulin resistance." (PMID 36291801, 2022). "We found the opposite relationship for each related disease for palmitate and TNF-α-induced insulin resistance conditions." (PMID 35055191, 2022). "Insulin resistance seems to promote the development of Th1 inflammation through the production of pro-inflammatory molecules (i.e., IL-6, TNF-α)." (PMID 35055456, 2022).
Insulin resistance (continued). "Our main results showed that FMT is a safe treatment that prevented body weight gain, reduced albuminuria, decreased local expression of TNF-α in the ileum and ascending colon, and potentially ameliorated insulin resistance in BTBRob/ob mice." (PMID 35409202, 2022). "But in an obese state, Ly6chigh monocytes infiltrate tissues and differentiate into M1 type macrophages, which produce inflammatory cytokines, such as TNF-α, IL-6, IL-1β, and IL-18, and drive insulin resistance." (PMID 36015301, 2022). "The inflammatory process partly mediates vascular complications in patients with diabetes, and there is evidence that IL-1β and TNFα are the major proinflammatory mediators in cell damage and insulin resistance." (PMID 36510592, 2022). "Factors that contribute to pregnancy-induced insulin resistance include the secretion of adipokines (e.g., leptin) and cytokines (e.g., tumor necrosis factor-alpha, interleukin-6, and interleukin-1β), oxidative stress and, possibly, the gut microbiome." (PMID 33536549, 2022). "Studies show that IL-17 can activate NF-κB pathway, upregulate TNF-α expression, and induce insulin resistance." (PMID 36452059, 2022). "On the other hand, an RCT of galantamine successfully reduced serum levels of TNF-α, increased levels of IL-10, and improved insulin resistance in patients with metabolic syndrome." (PMID 35858588, 2022). "Actually, the serum expression levels of sortilin are significantly altered in the mouse models with insulin resistance promoted by TNF-α or the intervention of dexamethasone." (PMID 34784266, 2022). "Chiefly, TNF-α is one of the main mediators of inflammation that strongly promote insulin resistance." (PMID 35811945, 2022). "We found that insulin resistance was the most significant enrichment pathway and was related to the mTOR, TNF, and MAPK pathways." (PMID 36077718, 2022). "Other pro-inflammatory cytokines can contribute to the development of MAFLD and colorectal tumors by inducing metabolic liver inflammation and insulin resistance through various complex inflammatory signaling pathways, such as IL-6 and TNFα." (PMID 35668493, 2022). "One mechanism by which GM3 induces insulin resistance is via the activation of an inflammatory pathway induced by tumor necrosis factor α (TNF-α)." (PMID 36499769, 2022). "Increased inflammatory cytokines like TNF-α and IL-6 secreted by visceral adipocytes along with cytokines specific for adipocytes are the key players in inducing insulin resistance." (PMID 37654824, 2022). "Then, proinflammatory cytokines (IL-1β, TNF-α, and so on), and the oxidative stress response activated insulin resistance." (PMID 35457582, 2022). "In mice with chronic stress-induced insulin resistance, caffeic acid (5 and 10 mg/kg)decreased serum levels of glycosylated hemoglobin, tumor necrosis factor-α (TNF-α), and interleukin-1β (IL-1β)." (PMID 36614030, 2022). "Obesity and low-grade inflammation induce insulin resistance but a recent study showed that TNF-α inhibited insulin-stimulated glucose uptake in 3T3-L1 cells, while knockdown of BRD2 maintained their insulin sensitivity." (PMID 36015180, 2022). "The phosphorylation of RhoA was decreased in palmitate-induced insulin resistance, but was only marginally decreased in TNF-α induced insulin resistance." (PMID 35055191, 2022). "The virus is responsible for peripheral and hepatic insulin resistance due to increased TNF-α secretion and other pro-inflammatory cytokines that interfere in post-receptor insulin signaling pathways." (PMID 35315984, 2022). "IRW (Isoleucine–Arginine–Tryptophan), has antihypertensive and anti-inflammatory properties in cells and animal models and prevents angiotensin-II- and tumor necrosis factor (TNF)-α-induced insulin resistance (IR) in vitro." (PMID 35740257, 2022). "RES treatment also alleviates insulin resistance by reducing TNF-α, cytokeratin 18, and fibroblast growth factor 21 in patients." (PMID 35164043, 2022).
Insulin resistance (continued). "TNF can play a crucial role in the development of insulin resistance in different tissue types, with high glucometabolic relevance." (PMID 36648872, 2022). "Insulin resistance increases in patients with RA and is associated with accelerated coronary atherosclerosis, and TNF-α antagonists have been shown to improve insulin sensitivity and reduce insulin resistance in patients with RA." (PMID 36060429, 2022). "By contrast, in vivo analyses have shown improvement in insulin resistance by inhibiting the production of tumor necrosis factor alpha (TNF-α) or by reducing endoplasmic reticulum stress." (PMID 35054822, 2022). "After measuring cell viability, we selected 20 ng/mL of TNF-α as the optimal concentration for insulin resistance." (PMID 35055191, 2022). "Macrophages appear to be the principal source of pro-inflammatory cytokines such as IL-1β and TNFα that can confer insulin resistance in insulin-sensitive cells." (PMID 35955975, 2022). "Reactive oxygen species (ROS) production and the secretion of inflammatory cytokines like TNFα and C-C motif chemokine ligand 2 are elevated under conditions of excess nutrition, which eventually impairs insulin signaling and results in insulin resistance." (PMID 36207302, 2022). "In a murine model of T2D, CHM-273S mitigated high-fat diet-induced hyperglycemia and insulin resistance and improved low-grade inflammation by diminishing serum TNFα." (PMID 36297523, 2022). "Following adipocyte death, macrophages M1 (stimulators of pro-inflammatory factors and inducers of insulin resistance) produce inflammatory cytokines such as IL-6, TNF-α, IL-1β, and monocyte chemoattractant protein (MCP-1)." (PMID 35055456, 2022). "IL-6 affects chronic inflammation, fat metabolism, and insulin resistance, and the expression of IL-6 induces other inflammatory cytokines such as TNF-a and IL-1." (PMID 36616208, 2022). "Enriched diet with EPA/DHA reduced TNF-α, C-peptide, insulin resistance, resistin, and the plasma atherogenic index, but increased TC, LDL-c, VLDL-c, and TG without changes in HDL-c." (PMID 35036426, 2022). "First, in cancer patients, particularly those who suffer from cancer cachexia, insulin resistance often occurs as a result of the secretion and activation of several proinflammatory cytokines induced by cancer itself, such as TNF-α." (PMID 35406580, 2022). "HOMA-IR as an index of insulin resistance and LDL/HDL ratio as a risk ratio, and serum concentrations of FFA, TNF-alpha, and IL-6 as factors involved in insulin resistance, were measured in high-fat diet/STZ-induced type 2 diabetic (HFD/STZ-induced T2D) mice." (PMID 35145895, 2022). "Low IGF-II levels have been reported in obese children, especially in those with insulin resistance and increased inflammatory markers, such as IL-6 and TNF-a." (PMID 36292046, 2022). "Adipose tissue can secrete proinflammatory cytokines such as interleukin 6 (IL-6) and tumor necrosis factor alpha (TNFα), which contribute to insulin resistance (IR)." (PMID 35586621, 2022). "Hepatic and peripheral insulin resistance, increased lipolysis, relative insulin deficiency, and decreased glucose cellular uptake due to pro-inflammatory molecules such as interleukin 1 (IL-1), interleukin 6 (IL-6), and tumor necrosis factor α (TNF-α), may also contribute." (PMID 35268392, 2022). "The mRNA expressions of TNF-α, IL-6, and angiopoietin-like 4 (Angptl4), which are involved in insulin resistance, were shown to be higher in the adipose tissue of mice from the P. gingivalis-administered group." (PMID 36299624, 2022). "Insulin resistance and cardiovascular diseases, two conditions in which pro-inflammatory cytokines, such as tumor necrosis factor-alpha (TNF-α), are critically involved, are recognized comorbidities in obese subjects." (PMID 35406010, 2022).
Insulin resistance (continued). "Proinflammatory cytokines, whose production is markedly increased in psoriasis (TNF-α, IL-17, IL-23, and IL-6) all contribute significantly to insulin resistance in patients with psoriasis." (PMID 35743091, 2022). "Insulin resistance, in combination with dyslipidaemia and the subsequent inflammatory cytokine milieu, which includes reductions in adiponectin and increased TNFα, culiminates in hepatic lipogenesis." (PMID 35773644, 2022). "The concentrations of propionic acid and butyric acid were negatively correlated with blood glucose indicators and insulin resistance, and negatively correlated with serum IL-6 and TNF-α concentrations." (PMID 35745208, 2022). "TNF can induce apoptosis by promoting the release of inflammatory factors, and TNF-α is closely related to insulin resistance." (PMID 35656465, 2022). "Their activation is dependent on the same IKK-β implicated in the pathophysiology of insulin resistance, and results in PPAR-γ mediated secretion of IL-1β, TNF-α, IL-6, IL-12, and IL-23." (PMID 36615781, 2022). "We found that the AMPK pathway of N2a cells is regulated through modulation of the common molecular targets under palmitate- and TNF-α-induced insulin resistance." (PMID 35055191, 2022). "The results show that YPs played an important role in inhibiting insulin resistance induced by TNF-α or ROS." (PMID 36159471, 2022). "Hypertrophic adipose tissue secretes inflammatory cytokines such as IL-6 and TNF-α, which involve the pathophysiology of metabolic diseases like increased insulin resistance." (PMID 35469126, 2022). "The statistically significant differences between patients with/without MAC were higher HOMA C-peptide and C-peptide index for insulin resistance, higher TNF-α for inflammation, and lower estimated glomerular filtration rate." (PMID 36143268, 2022). "Specifically, insulin resistance in adipocytes induced by TNF-α and IL-6 attenuates the inhibitory effect of insulin on lipolysis and FFA release." (PMID 35406450, 2022). "Based on these results, insulin resistance is important for GS-induced endothelial dysfunction, and metabolic syndrome-related factors such as FFAs and TNFα render endothelial function vulnerable to repeated GSs." (PMID 35073378, 2022). "For example, FMT treatment improved multiple parameters including amelioration of insulin resistance, prevention of weight gain as well as reduction of tumor necrosis factor-α (TNF-α) and albuminuria in a mouse model." (PMID 36569149, 2022). "Long-term studies are required to further understand the impact of inhibiting postprandial plasma TNFα after bioactive yoghurt consumption, and its effects on vascular dysfunction and insulin resistance." (PMID 36364884, 2022). "TNFα, a regulated product of NF-κB and a strong activator of NF-κB, induces insulin resistance mainly through serine phosphorylation of insulin receptor substrate-1 (IRS1)." (PMID 36510592, 2022). "Treatment with AD-MSCs and AD-MSCs preconditioned with OXA were reported to decrease TNF-α and IL-6 levels significantly as compared to group II which can improve insulin resistance (p < 0.001)." (PMID 35083338, 2022). "TNF-α-induced insulin resistance was also tested on N2a cells in the same manner as in the palmitate experiment." (PMID 35055191, 2022). "Increased VAT levels of proinflammatory mediators, including MCP-1, IFN γ, TNF, and IL-6 induce insulin resistance (IR) in VAT." (PMID 35164764, 2022). "Neutrophils from T2D patients secrete higher amounts of IL-6 and TNF-α in response to lipopolysaccharide (LPS) stimulation, resulting in insulin resistance, which then increases the blood glucose concentration." (PMID 35741012, 2022). "Among the various pro-inflammatory cytokines, tumor necrosis factor-alpha (TNF-α) is one of the most important pro-inflammatory mediators that is critically involved in the development of insulin resistance and pathogenesis of T2DM." (PMID 35767589, 2022).
Insulin resistance (continued). "Previous studies report that circulating TNFα interferes with insulin signaling through its receptor, while TNFα knockout mitigates insulin resistance in obese mice." (PMID 36559697, 2022). "TNF-α increases lipolysis, thus increasing serum free fatty acids and thus favoring the development of insulin resistance." (PMID 35008925, 2022). "• Promotes energy consumption by stimulating the hypothalamus. • Correlation with high TNFα levels and insulin resistance. • Chemotaxis and monocyte infiltration in adipose tissue by the expression of CD11b and CD163." (PMID 35422689, 2022). "Increasing insulin resistance seen throughout gestation is primarily the result of placental secretion of tumor necrosis factor alpha (TNFa) and small contributions from maternal plasma cortisol and leptin." (PMID 36584051, 2022). "Excessive lipid accumulation was reported to induce insulin resistance in adipocytes, hepatocytes, and skeletal muscle cells by increasing the levels of various proinflammatory cytokines, including IL-1β, IL-6, TNFα, and MCP1." (PMID 35889886, 2022). "They trigger NF-κB and AP-1, produce IL-6 and TNF-α that affect insulin sensitivity by altering the expression of genes encoding IRS-1, GLUT-4, and PPAR-α and lead to insulin resistance." (PMID 36140983, 2022). "The BSME-treated, maturing, adipocyte-secreted proteins were detected with a decreased protein level of leptin, TNF-α, IL-6 and STAT-6, which are associated with insulin resistance and macrophage recruitment." (PMID 35209178, 2022). "From these results, we concluded that the integrin pathway of N2a cells is downregulated through modulation of the common molecular targets under palmitate-induced and TNF-α-induced insulin resistance." (PMID 35055191, 2022). "In this study, serum resistin, TNF-α, and leptin levels were dramatically reduced by SRPE-3-Cr(III) treatment, indicating SRPE-3-Cr(III) alleviated insulin resistance by inhibiting the secretion of serum resistin, leptin, and TNF-α from adipocytes." (PMID 37073221, 2022). "The representative compound of polycyclic aromatic hydrocarbons, TCDD, induces insulin resistance by inducing TNF-α to reduce the expression of adiponectin in C3H10T1/2 adipocytes." (PMID 35057794, 2022). "Subsequently, insulin resistance stemming from excessive caloric intake can stimulate proinflammatory mediators and cytokines such as TNF-α, IL-6 and CRP." (PMID 35252372, 2022). "Among the proinflammatory cytokines, TNF-α is well characterized to induce insulin resistance in cultured adipocytes and in mouse." (PMID 35198097, 2022). "The systemic levels of TNF-α and IL-6 are elevated in DM, and can directly promote insulin resistance." (PMID 35805932, 2022). "The results indicated that AIP1 modulated TNF-α production and insulin resistance in adipocytes via JNK and MAPK/ERK signaling." (PMID 35712257, 2022). "The adipokines released include interleukin-1, interleukin-6, resistin and TNF-α (tumor necrotic factor-alpha), the latter two being directly involved in promoting insulin resistance." (PMID 35563854, 2022). "TNF-α, a potent pro-inflammatory cytokine, shifts the phenotype of ATMs from M2 to M1, thus worsening adiposity to insulin resistance." (PMID 35885044, 2022). "First, TNF-α is involved in developing insulin resistance and promotes the progression of T2DM and its complications." (PMID 35979044, 2022). "TNFα upregulated CSE-hydrogen sulphide upregulation in 3T3L1 adipocytes and induced a downregulation of adipocyte glucose uptake and a decrease in insulin responsiveness, but hydrogen sulphide donors reversed TNFα-induced insulin resistance." (PMID 36568094, 2022). "Insulin sensitivity is enhanced by SIRT1 activation via reduction in the expression of proinflammatory genes and it attenuates the insulin resistance induced by tumor necrosis factor alpha (TNF-α)." (PMID 35163422, 2022).